BRCA2 (BRCA2 DNA repair associated)
Diseases named in the same sentence as BRCA2 in open-access papers (continued):
Sharing a sentence is not in itself a finding about the gene and the disease.
tumor (continued). "Importantly, however, olaparib-resistant tumours taken 24 hours after their final dose were negative for RAD51 foci, irrespective of tumour phenotype, confirming that despite components of the pathway being up-regulated, the HRR pathway is compromised in these Brca2 knockout tumours, as expected." (PMID 31080552, 2019).
adenocarcinoma (18 papers, 2014 to 2026). A common cancer characterized by the presence of malignant glandular cells. "An increased risk of PC has been found in Ashkenazi Jews in whom more than 2% carry germline mutations in BRCA1 or BRCA2 and in PC with intraductal histology that appear to have greater genomic instability compared to those with adenocarcinoma histology." (PMID 36793600, 2023). "Here, we describe a unique case of SBA harboring multiple, somatic and germline, BRCA2 mutations in a woman with an early‐onset adenocarcinoma of the duodeno‐jejunal flexure, suggesting a likely pathogenetic role of BRCA2 biallelic mutations in the SBA development." (PMID 40205657, 2025). "BRCA2 may be associated with adenocarcinoma given that eight BRCA2 PGV carriers with NSCLC in one study had this subtype of NSCLC, and that in the over 300 patients with NSCLC studied in the SAFIR02-lung trial, the only two identified BRCA2 PGV carriers had adenocarcinoma." (PMID 38539485, 2024). "In more advanced adenocarcinomas, however, BRCA2 and RAD51 were overexpressed in about 50% of the cases." (PMID 24641873, 2014). "IDC-P arises from the same ancestral clone as adenocarcinoma, but specific abnormalities, such as MYC amplification, occur earlier in BRCA2-mutant PCa." (PMID 39840193, 2024).
infection (13 papers, 2014 to 2026). The state of being infected such as from the introduction of a foreign agent such as serum, vaccine, antigenic substance or organism. "Consistent with cell inviability, BRCA2 deficiency led to an acute proliferation defect within the first few passages after Cre infection associated with cellular senescence and apoptosis." (PMID 28904335, 2017). "One can imagine that these and other viruses that access the nucleus during replication could feasibly interact with BRCA1 or BRCA2, driving the selection of variants that ultimately lead to decreased susceptibility to infection." (PMID 25011685, 2014). "Using this method, we demonstrate that a Cas9-induced DNA double-strand break within the VSG coding sequence can induce RAD51- and BRCA2-dependent VSG recombination with patterns identical to those observed during infection." (PMID 41951731, 2026). "For suppressed infection markers, one network (−log10p = 9) converging on BRCA1 and BRCA2 was identified." (PMID 26214306, 2015). "The network analysis of suppressed infection markers centered on BRCA1 and BRCA2, which have roles in cell cycle control and DNA repair." (PMID 26214306, 2015). "However, infection did not impact BRCA2 protein expression and no methylation in the BRCA2 promoter region was observed, thus it is currently unclear whether this activity has a functional impact in PCa and additional work is warranted." (PMID 41514871, 2025). "BRCA1, BRCA2, FANCI, and FANCD2 were substantially downregulated following WT-H. pylori infection, but not upon infection with the ΔcagA H. pylori strain, highlighting the CagA-dependence in their downregulation." (PMID 35163588, 2022).
gastrointestinal tumors (12 papers, 2017 to 2023). "In this study, we first showed that BRCA2 is mutated in ~7–10% of gastrointestinal tumors, and that it was significantly correlated with microsatellite instability." (PMID 32980867, 2020). "Taken together, these data led us to assume that BRCA2 deficiency was pivotal for developing gastrointestinal tumors." (PMID 32980867, 2020). "Our study unveils the role of BRCA2 loss in the development of gastrointestinal tumors and provides a potential therapeutic strategy to eliminate BRCA2 monoallelic and biallelic mutant tumors through mitomycin C." (PMID 32980867, 2020). "Collectively, Brca2 deficiency driven by Villin-Cre can boost gastrointestinal tumor formation when genome instability is increased." (PMID 32980867, 2020). "Moreover, an increased frequency of other malignancies, such as gastro-intestinal tumors, has been reported in families with mutations in the BRCA2 gene." (PMID 33484353, 2021). "Villin-driven Brca2 depletion promotes mouse gastrointestinal tumor formation when genome instability is increased." (PMID 32980867, 2020). "Next, we asked why BRCA2 monoallelic and biallelic mutant gastrointestinal tumor cells were hypersensitive to MMC." (PMID 32980867, 2020).
genetic disorder (11 papers, 2010 to 2025). "BRCA1-associated HGSOCs accounted for 48/63 (76%) patients with hereditary disease, while only 15/63 (24%) women were BRCA2 mutation carriers." (PMID 40547808, 2025). "FA syndrome is a genetic disorder caused by germline biallelic mutations in one of 13 genes (including FANCD1/BRCA2 and FANCN/PALB2) of the so-called FA/BRCA pathway; this pathway controls the repair of double strand-breaks and the response to DNA crosslinking agents." (PMID 20122277, 2010). "Alu-mediated deletions have been identified in other genetic disorders and also in other DNA repair/FA genes such as BRCA2 and FANCA." (PMID 26085575, 2015).
hematological malignancies (6 papers, 2019 to 2025). "In this sense, the relationship between BRCA2 mutation and hematological malignancies is remarkable." (PMID 38392574, 2024). "Although solid tumors cells are believed to be more dependent on BCL-XL than hematologic malignancies, our results suggest that some AML cases, for example, BRCA2- or IDH2-mutated, may need this particular protein more than the other BCL2 family members for their survival." (PMID 34202143, 2021).
cardiovascular disease (5 papers, 2012 to 2026). "We therefore tested the association of BRCA2 variants with clinical cardiovascular disease (CVD)." (PMID 22809218, 2012).
hematological cancer (4 papers, 2007 to 2025). "Independent and unrelated lines of investigation strongly implicate BRCA1 and BRCA2 deficiencies in hematologic cancers." (PMID 17683622, 2007).
benign tumor (2 papers, 2018 to 2021). "Therefore, it is not possible to ascertain whether her BRCA2 gene mutation had any role in her benign tumor formation." (PMID 33763108, 2021).
autosomal dominant disease (1 paper, 2011). Autosomal dominant form of disease.
kidney diseases (1 paper, 2023). "Furthermore, there is a clinical link between FA patients who have bi-allelic BRCA2 mutations and kidney diseases and malformations that has been appreciated but never understood." (PMID 36810461, 2023).
BRCA2 also shares sentences with these, for which no sentence is quoted: breast (28 papers); hereditary pancreatitis (10); Cowden syndrome (8); cystic fibrosis (5); familial atypical multiple mole melanoma syndrome (4); prostate (4); chromosomal instability syndrome (3); Cirrhosis (3); CNS tumors (3); colon adenocarcinoma (3); familial colorectal cancer (3); Gynecomastia (3); Hereditary Diffuse Gastric Cancer (3); Hodgkins lymphoma (3); Hypercholesterolemia (3); laryngeal carcinoma (3); oral cancer (3); primary peritoneal carcinoma (3); Adult onset (2); allergies (2); alveolar rhabdomyosarcoma (2); autosomal recessive disease (2); carcinosarcoma (2); cardiomyopathies (2); childhood leukemia (2); Colon (2); COVID-19 (2); diabetes mellitus type 1 (2); embryonal rhabdomyosarcoma (2); familial melanoma (2).
A further 210 diseases each share a sentence with BRCA2 in 2 papers or fewer.